CCL5 (C-C motif chemokine ligand 5)
Diseases named in the same sentence as CCL5 in open-access papers (continued):
Sharing a sentence is not in itself a finding about the gene and the disease.
infection (continued). "In assays for a panel of cytokines, infection with rPR/8 × KYGNS did not induce overexpression of pro-inflammatory cytokines (IL-6, CCL5, and IFN-γ) on the contrary to what was observed with the two other viruses." (PMID 27846859, 2016). "Conversely, there was no significant increase in mRNA expression of CCL5, CCL19, CCL20 and CCL21 chemokines after infection in both MyD88+/+ and MyD88−/− mice." (PMID 23374751, 2013). "CCR5, but not CCL5 or IFN-γ mRNA expression by fallopian tube-, uterus-, and cervix- derived lymphocytes were considerably higher than levels before infection." (PMID 18700040, 2008). "Finally, there was a group of cytokines and chemokines: TNF, IFNγ, CCL5, CXCL9, CXCL10 and CXCL13, which were early after infection elevated in the vaccinated but not detectable in the naive animals, suggesting an adaptive immune response as the trigger." (PMID 39472590, 2024). "Of the 21 analytes that were evaluated, 9 analytes (angiopoietin, CCL3, CCL5, CCL7, CCL12, CXCL10, and TNF-α) were significantly changed in response to infection in both non-pregnant and pregnant mice, and more robust response was, in general, noted in non-pregnant mice (p < 0.05)." (PMID 38104118, 2023). "Respiratory syncytial virus (RSV)-EVs contain both viral RNA and proteins and host RNAs and either induce the secretion of MCP-1, IP-10 and CCL5 by recipient monocytes or of CCL5, IP-10, TNF-α by airway epithelial cells, without leading to an active infection of these cells." (PMID 36674550, 2023). "A non-significant decrease in MIP-1α/CCL3, MIP-1β, RANTES/CCL5 and MCP-1 was observed in negative post-infection samples, which could be related to the resolution of the inflammatory response." (PMID 36482106, 2022). "However, another study performed using the hRSV Long strain showed that CXCL8 levels were not changed upon infection with hRSV, while CCL3 and CCL5 levels were increased." (PMID 30936869, 2019). "Regardless of the infection, TNF-α, IL-15, IL-18, and CCL-5 were absent or barely detected." (PMID 30420629, 2018). "In addition, we also measured levels of CXCL10 and CCL5, at various time points following HIV-1 pWT/BaL infection, and consistently were not able to measure induction of these cytokines (data not shown)." (PMID 23431237, 2013). "Thus, we hypothesized that the differential expression of Il6 and Tnf during the late stage of infection was not induced directly by NSP9 but rather by other antiviral genes (such as Ifnb, Isg15, and Ccl5) produced via the activated type I IFN pathway." (PMID 37854611, 2023). "The infection of MDMs with Mtb opsonized with hSAA-1, compared to the infection with nonopsonized bacilli, led to at least a 2-fold increase in the concentrations of CSF2, CSF3, IL-1α, IL-1β, IL-6, IL-12, CCL15, and TNF-α with the most potent 10-fold increase observed for CCL5." (PMID 37781389, 2023). "In vitro, MPXV infection of human cells does not induce interferon-stimulated gene (ISG) expression and further suppresses Tumour Necrosis Factor alpha (TNF-α), Interleukin 1 alpha and beta (IL-1α and β), C-C Motif Chemokine Ligand 5 (CCL5) and Interleukin 6 (IL-6) activation in primary fibroblasts." (PMID 35887214, 2022). "Similarly, in non-infected HIS-HUHEP mice, IL-1b, IL-12, IL-1Ra, IL-2R, CCL5, and IFN-γ, could be detected but did not significantly change post-infection." (PMID 28851562, 2017). "Interestingly, the cytokines whose levels were increased in HMA+ strains during mBMDM infection in vitro and in PECS ex vivo, including IL6, CCL5, and IL10, are not those that would be expected to change based on interference with known mitochondrial signaling pathways (i.e., MAVS, NF-kB, IRF3/7)." (PMID 24781109, 2014). "However, downregulation of host genes such as Ccl7, Ccl5 and Cxcl10 by TAT-I24 at early time-points of infection could not be reversed when infection was performed with UV-irradiated MCMV, which was not able to induce viral gene expression due to severely damaged DNA." (PMID 35806257, 2022).
infection (continued). "Since we had observed production of higher levels of CCL3 and not the CCL4 and CCL5 chemokines by LdCen-/ -infected neutrophils, we therefore assessed whether chemo-attractive activity of CCL3 itself is necessary and sufficient to explain the elevated DC migration observed in LdCen-/- infection." (PMID 35192633, 2022).
cancer (690 papers, 2008 to 2026). A tumor composed of atypical neoplastic, often pleomorphic cells that invade other tissues. "Blocking MALAT-1 in the CCL5/MALAT-1/Snail axis prevented Snail overexpression from causing CCL5-induced migration and invasion, demonstrating the vital of this axis in the DC-dependent cancer development." (PMID 39944836, 2025). "While some research suggested that high CCL5 expression was associated with T cell exhaustion in other cancers, other studies reported that high CCL5 expression in tumors correlates with increased T cell activity." (PMID 41155216, 2025). "Our study investigated the prognostic significance of CCL5 time series expression and its association with various immune gene signatures in cancer patient survival analysis." (PMID 41301844, 2025). "Cisplatin-induced DNA damage promotes a cGAS-STING–dependent senescence program in cancer-associated fibroblasts (CAFs), resulting in the secretion of CCL5, a key senescence-associated secretory phenotype factor." (PMID 41152972, 2025). "The C-C motif chemokine receptor 5 (CCR5)/C-C motif chemokine ligand 5 (CCL5) axis has been implicated in an autocrine and paracrine fashion to stimulate cancer cell proliferation, metastasis, and immune regulation." (PMID 39199569, 2024). "Although CCL5 can drive inflammatory responses, it is frequently implicated in promoting malignancy and is associated with poor prognosis in cancers such as prostate, breast, lung, and melanoma." (PMID 39409924, 2024). "In particular in BC, chemokine CCL5 secreted from Tumor Associated Macrophages contributes to cancer malignancy supporting epithelial–mesenchymal transition and aerobic glycolysis." (PMID 39501160, 2024). "For example, CCL5 is involved in angiogenesis and is associated with the increased expression of vascular endothelial growth factor in cancer cells and vascular endothelial cells." (PMID 37141250, 2023). "Several studies have found an association between CCL5 polymorphisms and decreased risk of cancer and other diseases." (PMID 36983384, 2023). "On the one hand, overexpression of CCL5 or CCR5 in cancer cells has been found to be associated with poor prognosis." (PMID 37040518, 2023). "Elevated Ccl5 expression was associated with cancer-related inflammation in RCC cell lines and poor clinical prognosis in patients with RCC." (PMID 36132332, 2022). "A significant association between transcriptomic CCL5 expression and macrophages has been identified among 33 cancer types in the TCGA database." (PMID 35982911, 2022). "HT also modulated cancer-associated-fibroblasts by suppressing the Chemokine C-C motif ligand 5 (CCL5), thus inhibiting fibroblast-stimulated MCF-7 cell proliferation." (PMID 35056792, 2022). "CCL5 is associated with a variety of biological processes and its expression in a variety of different tumors has implications for the development of cancer." (PMID 36387070, 2022). "Of the CC chemokines, CCL2, CCL4 and CCL5 have all been implicated in cancer development and metastasis formation." (PMID 36241867, 2022). "Another previous study revealed a close association between the CXCL9 and CCL5 expressions in OV and other cancers." (PMID 33869044, 2021). "High levels of pro-inflammatory chemokines, e.g. CCL2 and CCL5, in circulation are associated with poor prognosis for cancer patients." (PMID 34868988, 2021). "Considering other CC subfamily chemokines, CCL2 and CCL5 have also been implicated in the progression of a wide range of cancers." (PMID 34206004, 2021). "The induction of migration by CCL5 is associated with increased secretion of matrix metalloproteinases (MMPs) by cancer cells." (PMID 33076281, 2020). "CCL5 is secreted by diffuse large B cell lymphoma, which causes the recruitment of monocytes that increase the proliferation of those cancer cells." (PMID 33076281, 2020). "Compelling evidences indicate that CCL5 is associated with tumourigenesis and metastasis in several types of cancer." (PMID 27166194, 2016).
cancer (continued). "CCL5 production is relevant to inducing proper immune responses against tumors, but, on the other hand, CCL5 is associated with cancer progression and metastasis." (PMID 24523569, 2014). "CCL5 is associated with chronic inflammatory diseases such as rheumatoid arthritis, inflammatory bowel disease, and cancer." (PMID 22506069, 2012). "An association between CCL5 expression and cancer has been reported in melanoma, lung, prostate, and pancreatic cancers." (PMID 22506069, 2012). "For example, Ccl5/Rantes enhances inflammatory processes and has been associated with the induction or promotion of cancer." (PMID 20059583, 2010). "The accumulation of various immune cell types observed in Ang II-infused WT hearts was notably reduced by CCL5 KO, including memory B cells, macrophages/monocytes, cancer-associated fibroblasts, CD8+ T cells, myeloid dendritic cells, M2 macrophages, regulatory T cells, and NK cells." (PMID 41346713, 2026). "Expression of CCR5 or CCL5 is broadly linked to poor prognosis in cancer, due in part to the promotion of MDSCs, plus genetic and metabolic alterations to antitumor immune cells and cancer cells, angiogenesis, and ECM remodeling." (PMID 38786066, 2024). "CCL5 is associated with the STAT3 signaling pathway in several types of cancer." (PMID 39126553, 2024). "Several studies have found an association between CCL5 variants and an increased risk of cancer." (PMID 36983384, 2023). "CCL5-deficient NK and helper T cells (Th) were shown to be less efficient in recruiting dendritic cells (DCs) and cytotoxic T lymphocytes to cancer sites, resulting in increased cancer development." (PMID 32218434, 2020). "CCL5 may cause differentiation of cancer stem cells into endothelial cells as observed in the ovarian cancer model." (PMID 33076281, 2020). "Moreover, the interaction of cancer cells and MSCs induces the transformation of MSCs into cancer-associated fibroblasts through the production of CCL5 and osteopontin, promoting tumour progression." (PMID 31511776, 2019). "CCL5 is a target gene of NF-κB, associated with cancer progression and metastasis." (PMID 31200663, 2019). "Notably, in human cancer biopsies, the transcript levels of CCL5, XCL1, and its paralog XCL2 are associated with a cDC1-specific gene signature, suggesting a similar role for these chemokines in attracting cDC1s into human tumors." (PMID 30352680, 2018). "Since tumorigenesis is associated with inflammatory response, elevated CCL5 secretion by RCC cells may be part of cancer-related inflammation." (PMID 28775934, 2017). "CCL5 is a chemokine that has been associated to several forms of cancer." (PMID 27027351, 2016). "Furthermore, we found the expression of inflammatory chemokines, particularly CCL5, was strongly correlated with immune activity and associated with poor survival, particularly in these cancers, suggesting that these inflammatory mediators are potential molecular targets for therapeutics." (PMID 35525921, 2022). "In addition, neutralization of CCL5 may help to reduce the risk of lung metastasis in cancer patients under radiotherapy." (PMID 32382015, 2020). "However, knowledge of CCL5 implications with regard to cancer susceptibility remains elusive." (PMID 31921621, 2019). "Studies have confirmed that HDAC1 inhibition reinstated CCL5-driven CD8+ T cell recruitment in cancer." (PMID 40475010, 2025). "Ovarian cancer-TA-MSCs-derived CCL2 and CCL5 increase IL-6 expression in cancer cells, promoting chemotherapy resistance via PYK2 phosphorylation." (PMID 40676710, 2025). "In the second loop, TA-MSCs enhance cancer cells secretion of CSF1 by releasing CCL5, which binds to CCR5 on cancer cells." (PMID 40676710, 2025). "MSCs overexpressing SIRT1 significantly expedited cancer initiation and progression by secreting CCL5, which enhanced macrophage recruitment and amplified the inflammatory response." (PMID 40676710, 2025).
cancer (continued). "Previous studies have also shown that high intratumoral expression of CCL5, a CD8+ T cell-associated chemokine, is associated with a better prognosis in various cancers." (PMID 41049003, 2025). "GNG4 and CCL5 are involved in multiple facets of cancer biology, including cell proliferation, migration, and immune cell recruitment." (PMID 40395456, 2025). "This is consistent with other findings, including reports from our research group, describing the involvement of IL-8 and CCL5 in cancer progression and aggressiveness." (PMID 41409302, 2025). "Several cell types within the TME, including both immune and cancer cells, are significant producers of the chemokines CCL5 and CXCL10." (PMID 40248897, 2025). "Research indicates that cancer‐associated fibroblasts (CAFs) secrete elevated levels of CCL2, CCL5, CCL7, and CXCL16, which facilitate the migration and invasion of HCC cells." (PMID 40062588, 2025). "Correlation analysis revealed that CCL5 correlated significantly with Stat1 in TCGA pan‐cancer data." (PMID 40995650, 2025). "In contrast, CCL5 was notably downregulated (0.4-fold) in cancer cells, possibly indicating immune evasion mechanisms." (PMID 40395456, 2025). "This upregulation of ISGs upon ORMDL3 knockdown was consistent in the MC38 cancer model, where Ifnb1, Ccl5, and Cxcl10 mRNA levels were significantly elevated." (PMID 40126553, 2025). "Studies have shown that CCR5 antagonists, especially when combined with immune checkpoint inhibitors or CAR-T cell therapy, can improve immunotherapy outcomes in various cancers, making the CCL5/CCR5 pathway a promising strategy for the treatment of GC." (PMID 41376630, 2025). "Pan-cancer analysis revealed that CD58 was associated with key immune regulatory factors, including PD-L1, chemokines (CCL5, CXCL9, CXCL10)." (PMID 41438981, 2025). "Both MSCs and A431 cells secreted MIF, SERPIN1, IL-8, and CXCL1/GRO⍺, while CCL2 and IL-6 were only found in MSC cultures, and CCL5 and GM-CSF were only detected in cancer cell supernatants." (PMID 38674102, 2024). "In the ctcRbase database, we selected different types of cancers and compared the CCL5 expression level in sequencing data." (PMID 39227943, 2024). "M-E4BP4 showed increased expression of anti-inflammatory genes such as Retnla, IL10, and C1qa, and Ccl5, which is involved in immune escape of cancer, and decreased expression of pro-inflammatory genes such as Txnrd1, Odc1, Mmp1232,36–40." (PMID 38714733, 2024). "Several CC chemokines, such as CCL1, CCL2, CCL5, CCL18, and CCL21, have been implicated in cancer, exhibiting both pro- and anti-tumorigenic roles." (PMID 39409924, 2024). "The analysis from the ctcRbase database suggested that CCL5 expression in CTCs was consistently high across different cancers." (PMID 39227943, 2024). "In the TME, CCL5 or CCR5 overexpression is reported in many cancers such as head and neck, breast, prostate, pancreatic, esophageal, gastric, colorectal, and hematological malignancies." (PMID 39329983, 2024). "TANs secreted abundant amounts of chemokine ligand 5 (CCL5), subsequently enhancing cancer cell migration and invasion." (PMID 39261943, 2024). "In our research, we discovered that MIR155HG can recruit more CD8+ T cells by CCL5, both in vivo and in vitro, through immunohistochemistry and T cell recruitment assay, thereby mitigating its own cancer-promoting effects." (PMID 39043648, 2024). "ERα signaling in CAFs has been shown to decrease the expression of specific cytokines and chemokines, such as CCL5 (also known as RANTES) and IL-6, that disrupt macrophage infiltration and cancer cell invasion." (PMID 38715072, 2024). "In Nf1OPG mice, we elucidated a “neuron-immune-cancer cell” circuit, where T cells are induced by Nf1-mutant neuron-produced midkine to express Ccl4, which stimulates TAMs to secrete Ccl5, a key growth factor for Nf1-OPG development and progression." (PMID 38308315, 2024).